PIK3R2 (phosphoinositide-3-kinase regulatory subunit 2)
Diseases named in the same sentence as PIK3R2 in open-access papers (continued):
Sharing a sentence is not in itself a finding about the gene and the disease.
cancer (64 papers, 2010 to 2025). A tumor composed of atypical neoplastic, often pleomorphic cells that invade other tissues. "The previous study on PIK3R1/2 gene expression in various malignant tumors has shown that PIK3R2 is highly expressed in most tumors and is associated with poor prognosis in certain types of malignancies." (PMID 40504311, 2025). "Our findings also suggested PIK3R1 and PIK3R2 expression both had positive correlations with cancer-associated fibroblasts in the majority of tumors." (PMID 35395865, 2022). "On the contrary, PIK3R2 expression in most tumors was positively related to cancer-associated fibroblasts." (PMID 35395865, 2022). "We also presented comprehensive evidence of the relationship between PIK3R1 as well as PIK3R2 and immune infiltration levels of six immune cells and cancer-associated fibroblasts in TCGA tumors." (PMID 35395865, 2022). "The results indicated that PIK3R1 expression was positively associated with the infiltration level of immune cells in the majority of tumors, by contrast, PIK3R2 expression was negatively associated with immune infiltration level in most cancer." (PMID 35395865, 2022). "PIK3R2, a gene encoding p58β regulatory subunits that participated in most of the cancer-related and biological activity signaling pathways including PI3K, mTOR and cell cycle-apoptosis." (PMID 34299042, 2021). "PIK3R2 encodes the p85β regulatory subunit of phosphatidylinositol 3-kinase and is frequently amplified in cancers." (PMID 32385243, 2020). "Mutations of PIK3R1 and/or PIK3R2 are also found in cancer cells resulting in the altered expression of PI3K." (PMID 29755656, 2018). "In cancer, the p85a subunit is frequently reduced in expression or mutated, leading the catalytic subunit p110 to associate with another regulatory subunit p85b, encoded by the gene PIK3R2, leading to high levels of PI3K lipid kinase activity." (PMID 40564017, 2025). "Moreover, not only mutations, downregulation of PIK3R1 and upregulation of PIK3R2 were found to be detrimental to the survival of most cancer patients as well." (PMID 35395865, 2022). "Intriguingly, de novo germline and postzygotic, somatic mosaic mutations in similar locations in PIK3CA and PIK3R2 (p85β) also lead to overgrowth and developmental disorder syndromes, revealing that the same mutant can lead to cancer and/or developmental disorders." (PMID 29616047, 2018). "Overall, PIK3R1 expression was lower in most cancers while PIK3R2 was higher compared with the corresponding control tissue." (PMID 35395865, 2022). "Among them, PIK3R1 and PIK3R2 plays opposite roles in 6 cancer types and similar roles in 3 cancer types." (PMID 35395865, 2022). "We further explored the PIK3R1 and PIK3R2 genetic alteration status in human cancers of TCGA cohorts using cBioPortal." (PMID 35395865, 2022). "In the present study, the transcriptional expression levels of PIK3R1 and PIK3R2 genes in pan-cancer were first visualized using the TIMER and GEPIA database." (PMID 35395865, 2022). "Our study conducted a comparatively comprehensive analysis of the role of PIK3R1 and PIK3R2 in a variety of cancers, contributing to further study of their potential mechanisms in cancer occurrence and progression." (PMID 35395865, 2022). "Meanwhile, it suggested that besides gene mutations, decreased or increased mRNA expression levels of PIK3R1 and PIK3R2 are supposed to be considered in clinical management of cancer." (PMID 35395865, 2022). "It is essential for cancer treatment and management to clarify the regulatory mechanism of c‐Met/PIK3R2." (PMID 32395869, 2020). "Phenotypic studies using cancer models have demonstrated that PIK3R2 depletion decreases the viability of a breast cancer cell line in vitro and hampers colon carcinogenesis in Pik3r2−/− mice." (PMID 32385243, 2020). "Since, increase in PIK3R2 expression has been reported in several cancers we believe the findings of MWCNT are of considerable significance." (PMID 29755656, 2018).
cancer (continued). "Some studies have revealed that miR-126-3p inhibits cancer growth directly by targeting Sox2, p85β (PIK3R2), IRS1, VEGF and other genes." (PMID 27191494, 2016). "Via PI3K/AKT signaling pathway which functions in angiogenesis, invasion, metastasis and survival, miR-126 probably directly regulated its direct target PIK3R2 to complete the connection between inflammation and cancer." (PMID 26489668, 2015). "Other genes we found to be altered by miR-126-3p expression include PIK3R2 and CAMSAP1, which have also been implicated in cancer biology." (PMID 26244545, 2015). "RAB3A and PIK3R2 were found to be co-expressed in human cancers." (PMID 41408150, 2025). "Our findings suggested that PIK3R1 and PIK3R2 could serve as prognostic markers for several cancers." (PMID 35395865, 2022). "Notably, the expression of PIK3R1 and PIK3R2 were significantly correlated with the prognosis of 13 and 12 cancer types, respectively." (PMID 35395865, 2022). "Interestingly, PIK3/AKT signaling cascade is specifically targeted by the onco-suppressor miR-126, as it is well documented that IRS-1 and PIK3R2, two upstream components of this pathway, are directly inhibited by miR-126 in several cancer types, including BC." (PMID 35628294, 2022). "The protein subnetwork of PIK3R2 could be used for further pan-cancer studies in the future: DUSP10, DUSP6, FHL2, IRS2, PIK3R2, and RIPK2." (PMID 36329531, 2022). "Thus, a comprehensively understanding of the function of PIK3R1 and PIK3R2 in tumors will be necessary to develop better therapies and so we performed a pan-cancer analysis of them." (PMID 35395865, 2022). "PIK3R2 belongs to a family of genes known to be involved in pan-cancer." (PMID 36329531, 2022). "Increased PIK3R2 expression has been found in cancer, and it has been proposed as an oncogene." (PMID 33785040, 2021). "Our findings that AXL mediates the oncogenic signaling of p85β provide further support for targeting AXL as a cancer treatment and suggest that PIK3R2 amplification could serve as a biomarker for the efficacy of AXL inhibitors." (PMID 32385243, 2020). "In addition, the Rbx1, Hdac2, and Pik3r2 are involved in the signaling pathway of cancer cells." (PMID 35468821, 2022). "However, the role of PIK3R1 or PIK3R2 in some other cancers and whether PIK3R1 or PIK3R2 can play a role in the pathogenesis of different tumors through certain common molecular mechanisms remains to be explored." (PMID 35395865, 2022). "PIK3R2 plays a crucial role in regulating cell growth, survival, proliferation, motility, and morphological dynamics, while GRB2 is involved in cancer cell mobility, migration, and invasion through growth factor signal transduction." (PMID 40733070, 2025). "The regulatory subunits (p85) of PI3K also exhibited significant roles; p85α (PIK3R1) acted as a tumor suppressor with reduced expression in cancer, whereas p85β (PIK3R2) functioned as an oncogene, showing heightened expression in cancers." (PMID 38287309, 2024). "Such as PIK3R2, a Key regulatory subunit of PI3K, which was considered an oncogene in several cancers." (PMID 36450891, 2023). "The ALDO regulomes (sets of significantly regulated genes in this pathway) of the three cancer nodules are different, with only one gene, PIK3R2 (phosphoinositide-3-kinase, regulatory subunit 2 (beta)), being significantly up-regulated in all three nodules." (PMID 38132440, 2023). "PIK3R2 and FN1 resulted being the proteins with the highest number of protein-protein interactions, and therefore can be considered as pan-cancer gene hubs." (PMID 36329531, 2022). "the PI3K regulatory subunits PIK3R2/p85beta and PIK3R3/p55gamma, are frequently overexpressed in various cancers." (PMID 35459184, 2022). "Through our pan-cancer analysis of PIK3R1 and PIK3R2, this study revealed the important role of their aberrant expression in carcinogenesis and patient survival that warrant further investigation." (PMID 35395865, 2022).
cancer (continued). "It would be interesting to determine the co-occurrence of Gas6 elevation and PIK3R2 amplification, as well as the corresponding AXL activation status in cancer patients." (PMID 32385243, 2020). "This included genes like, PIK3R2, PIK3CA, BIRC2 and ZBTB14 with implications in cancer that were over-expressed with FC above ≥10 in OS-DW in comparison to OS-R; while, expression of WNT5A, PIK3CB, ACVR1, MAPK13 and GBX2 were significantly reduced." (PMID 31690262, 2019). "Mutations and/or amplifications of the PI3K catalytic subunits p110α (PIK3CA) and p110β (PIK3CB), the PI3K regulatory subunits p85α (PIK3R1) and p85β (PIK3R2), the PI3K effector AKT (AKT1) are often observed in cancer." (PMID 23658859, 2013). "The pan-cancer study comprehensively investigated the gene expression, genetic alteration, DNA methylation, and prognostic significance of PIK3R1 and PIK3R2 in 33 different tumors based on the TIMER, GEPIA, UALCAN, HPA, cBioPortal, and Kaplan–Meier Plotter database." (PMID 35395865, 2022). "Although PIK3R1 and PIK3R2 have been shown to serve opposite roles as tumor-suppressor gene and oncogenes in multiple tumors, evidence of their role in pan-cancer is lacking." (PMID 35395865, 2022). "The KEGG pathway results suggested that “ERBB signaling pathway”, “Proteoglycans in cancer”, “Ras signaling pathway” and “PI3K-Akt signaling pathway” may participate in the effect of PIK3R1 and PIK3R2 in tumorigenesis." (PMID 35395865, 2022). "The expression of PIK3R2 is reduced by miR-30a-5p upregulation, leading to NSCLC apoptosis and the inhibition of invasiveness and migration, therefore highlighting a potential role of this miRNA as a novel cancer treatment." (PMID 34948154, 2021). "Evidence showing that PIK3R2 represses PI3KAKTsignaling in ECs but enhances PI3K-AKT signalingin cancer cells, is not sufficient." (PMID 29633591, 2018). "Finally, we failed to obtain correlations between PIK3R1 or PIK3R2 expression and prognosis of other cancers." (PMID 35395865, 2022). "Meanwhile, increased PIK3R2 expression predicted better OS for CESC (HR = 0.50, P = 0.0038), TGCT (HR = 0, P = 0.0095) and better RFS for CESC (HR = 0.4, P = 0.02) and PCPG (HR = 0, P = 0.032), but we did not observe that PIK3R1 significantly influenced the prognosis of these three cancers." (PMID 35395865, 2022). "in vitro studies showed that PTPN1 can mediate dephosphorylation of c‐Met and PIK3R2 by binding with both, thereby weakening cell proliferation, metastasis and erlotinib resistance, while CAPN1 could enhance the degradation of PTPN1 protein as a cancer promoter." (PMID 32395869, 2020). "Through literature review, we failed to retrieve any publication with a pan-cancer analysis of PIK3R1 and PIK3R2 from the perspective of overall tumors." (PMID 35395865, 2022).
infection (8 papers, 2010 to 2024). The state of being infected such as from the introduction of a foreign agent such as serum, vaccine, antigenic substance or organism. "The downregulated genes associated with the ADM pathway included MAPKs, PLCs, the PIK3R2, the guanylate cyclase C, implicated in infection and inflammation control and the IL1RN, which encodes the anti-inflammatory protein IL-1Ra." (PMID 38241313, 2024). "It was found that the expression of PIK3CD decreased continuously, while the expression of PIK3R2 increased and then decreased during infection." (PMID 36439120, 2022).
cardiovascular diseases (2 papers, 2022 to 2025). "In addition, studies have suggested that miR‐126 targets PIK3R2 to inhibit endothelial progenitor cells (EPC) in endothelial mesenchymal transition (EndMT), which may become a therapeutic tool for cardiovascular diseases." (PMID 40631874, 2025).
inflammation (1 paper, 2018). Aberrant reaction of the microcirculation characterized by movement of fluid and leukocytes from the blood into extravascular tissues. "Apart from Spred-1, PIK3R2 andEGFL7, miR-126 targets vascular cell adhesion protein 1(VCAM-1), thereby affects the regulation of the adhesionof leukocytes to the endothelium defining anotherrole for miR-126 in vascular inflammation." (PMID 29633591, 2018).
neurodegenerative disease (1 paper, 2024). A disorder of the central nervous system characterized by gradual and progressive loss of neural tissue and neurologic function. "Recently, changes in miRNA expression have also been linked to various neurodegenerative diseases, providing new hope for diagnosing and differentiating DLB; for example, the pathological link between the genes BCL2L1 and PIK3R2 has been further supported." (PMID 39116438, 2024).
PIK3R2 also shares sentences with these, for which no sentence is quoted: glioblastoma (3 papers); leukemia (3); metastatic melanoma (3); bladder carcinoma (2); capillary malformation (2); Cognitive impairment (2); Hypoglycemia (2); influenza (2); Macrocephaly (2); renal cell carcinoma (2); thyroid cancer (2); adenocarcinoma (1); Arthritis (1); atherosclerosis (1); autism (1); chronic lymphocytic leukemia (1); chronic myeloid leukemia (1); chronic obstructive pulmonary disease (1); COVID-19 (1); deep vein thrombosis (1); depression (1); diabetic nephropathy (1); dysplasia (1); endometrial adenocarcinoma (1); Epstein-Barr virus infection (1); esophageal cancer (1); genetic disorders (1); Histiocytosis (1); human papillomavirus infection (1); hyperglycaemia (1).
A further 22 diseases each share a sentence with PIK3R2 in 1 paper.